SCN4B (sodium voltage-gated channel beta subunit 4)
Diseases named in the same sentence as SCN4B in open-access papers (continued):
Sharing a sentence is not in itself a finding about the gene and the disease.
cancer (9 papers, 2016 to 2024). A tumor composed of atypical neoplastic, often pleomorphic cells that invade other tissues. "The loss of SCN4B/β4 enhances cancer cell migration and metastases formation through a RhoA-dependent signalling pathway, independently of pore-forming NaV subunits." (PMID 27917859, 2016). "At the cellular level, the loss of SCN4B/β4 in cancer cells further stimulates their invasiveness by favouring amoeboid migration, supported by the overactivation of the RhoA pathway, yet keeping the ECM-degradative activity intact." (PMID 27917859, 2016). "In conclusion, this study shows that the loss of SCN4B gene expression in cancer cells promotes the acquisition of an amoeboid–mesenchymal hybrid phenotype, while its overexpression reduces both mesenchymal and amoeboid invasive capacities." (PMID 27917859, 2016). "Therefore, we initially hypothesized that loss of SCN4B expression would increase NaV1.5 activity in highly aggressive cancer cells." (PMID 27917859, 2016). "This suggests that SCN4B/β4 is normally expressed in normal epithelial cells (also confirmed by immunohistochemical analyses of normal oesophagus and that its loss of expression is associated with a gain in invasive properties by cancer cells and an aggressive progression of epithelial tumours." (PMID 27917859, 2016). "Metastasis is one of the reasons for the low survival rate in LUAD, and SCN4B is proven to be a metastasis‐suppressor gene in many cancers, including lung cancer." (PMID 37826914, 2023). "Through differential expression analysis between tumor and normal samples in TCGA‐LUAD, SCN4B was found to be significantly lower expressed in cancer samples." (PMID 37826914, 2023). "As a metastasis‐suppressor gene in many other cancers, SCN4B also inhibited the progression of LUAD." (PMID 37826914, 2023). "The expression of the SCN4B gene was shown to be lower in highly invasive cancer as compared with weakly invasive or non-cancer cells." (PMID 34209614, 2021). "In this study SCN4B mRNA appeared to be significantly expressed in normal breast, colon, rectum, lung, and prostate but consistently downregulated in cancer samples." (PMID 33817575, 2021). "Similar to SCN4B, the low expression of Tubulin alpha 4b (TUBA4B) has also been shown to be significantly associated with poor prognosis of cancer patients." (PMID 33902636, 2021). "Together, these recent studies brought new elements on the involvement of miRNA in the promotion of cancer progression through the regulation of the SCN4B expression in tumours." (PMID 34209614, 2021). "In contrast, overexpression of SCN4B/β4 reduced the aggressiveness of cancer cells, tumor growth, and metastasis progression." (PMID 30895169, 2019). "The overexpression of SCN4B gene, confirmed by qPCR and western blotting experiments, significantly reduced cancer cell invasiveness by 51.6±6.8% (n=6) in oeSCN4B as compared with control cells and by about 82% as compared with shSCN4B cells." (PMID 27917859, 2016). "All together, these results indicate that the overexpression of SCN4B in cancer cells reduces primary tumour growth and metastatic colonization." (PMID 27917859, 2016). "The reintroduction of the full-length SCN4B/β4 protein significantly reduced cancer cell invasiveness as compared with the empty vector (pSec), and as such, performed as an effective rescue." (PMID 27917859, 2016). "Here, we identified the SCN4B gene as an important modulator of RhoA activity and invasiveness in cancer cells." (PMID 27917859, 2016). "Initial immunohistochemical analyses performed in normal and cancer breast tissues indicated that the SCN4B/β4 protein was specifically expressed in epithelial cells from normal mammary acini, but was significantly downregulated in cancer cells." (PMID 27917859, 2016). "In this study, we show that the SCN4B/β4 subunit is expressed in normal epithelial cells and tissues, but is strongly downregulated in aggressive cancer cells and tumours." (PMID 27917859, 2016).
cancer (continued). "This study also demonstrates that the SCN4B/β4 protein acts both as NaV pore-subunit regulator and as RhoGTPases regulator in cancer cells." (PMID 27917859, 2016). "Conversely, SCN4B overexpression reduces cancer cell invasiveness and tumour progression, indicating that SCN4B/β4 represents a metastasis-suppressor gene." (PMID 27917859, 2016). "Conversely, the overexpression of SCN4B/β4 reduces cancer cell invasiveness, tumour growth and metastatic progression, supporting our proposal that the SCN4B gene is a metastasis-suppressor gene." (PMID 27917859, 2016). "As a tumor suppressor gene, SCN4B plays a role in various cancers." (PMID 38877096, 2024). "In contrast, SCN4B overexpression can reduce cancer cell invasiveness and tumor progression." (PMID 37826914, 2023). "On the contrary, SCN4B overexpression reduced cancer cell invasiveness and tumor progression." (PMID 33817575, 2021). "The SCN4B gene, coding for the NaVβ4 subunit of voltage-gated sodium channels, was recently found to be expressed in normal epithelial cells and down-regulated in several cancers." (PMID 34209614, 2021). "Interestingly, recent studies pointed out the involvement of several miRNAs that are dysregulated in some cancers as important regulators of the SCN4B expression." (PMID 34209614, 2021). "Furthermore, the expression of SCN4B/β4 is reduced in cancer tissues, and more specifically when tumours gain invasive properties (transition from grade I to grade II)." (PMID 27917859, 2016). "The expression level of SCN4B could therefore represent an important prognosis marker in cancers from epithelial origin." (PMID 27917859, 2016). "In both experiments, the downregulation of SCN4B importantly potentiated the capacity of cancer cells to migrate through a monolayer of endothelial cells, after having invaded (invasion), or not (migration), a layer of matrigel, as compared with shCTL or oeSCN4B cells." (PMID 27917859, 2016). "Importantly, SCN1B and SCN4B genes appeared to be the two most highly expressed SCNxB genes in non-cancer tissues." (PMID 27917859, 2016). "Because the reduced expression of SCN4B increases cancer cell aggressiveness, we investigated whether its stable experimental overexpression (oeSCN4B) could have opposite effects." (PMID 27917859, 2016). "Indeed, the suppression of SCN4B gene expression in cancer cells reduced the peak sodium current due to NaV1.5 activity." (PMID 27917859, 2016). "In contrast, the 176 passager genes were biased toward functions developed with cancer progress, such as their top genes, SCN4B and SLIT3, which controlled cancer cell migration, and the ABCA8 gene that related to cancer chemoresistance." (PMID 38666214, 2024). "However, what could trigger the repression of SCN4B during cancer transformation is still unknown." (PMID 34209614, 2021). "SCN4B mRNA was expressed in cancer H23 and non-cancer NL-20 and BEAS-2B but not in H460, Calu-1, and A549." (PMID 33817575, 2021). "In this study, we confirmed that SCN4B/NaVβ4 is downregulated in cancer compared with non-cancer cells and tissues." (PMID 34209614, 2021). "Recently, in the study of breast cancer, it was first demonstrated that SCN4B /β4 protein is expressed in non-cancer epithelial cells, but expression was reduced in cancer tissues, and was almost absent in high-grade tumors and metastases." (PMID 30895169, 2019). "Altogether, there was a strong reduction in lung colonization by cancer cells overexpressing SCN4B/β4 compared with non-expressors." (PMID 27917859, 2016). "Overexpressing SCN4B did not affect cancer cell growth and viability." (PMID 27917859, 2016).
tumor (8 papers, 2014 to 2024). "The expression of SCN4B in tumor samples with different pathological stages (I, II, III, IV) was analyzed, and the results showed the expression level became much lower as the stage passed by from stage I to stage III." (PMID 37826914, 2023). "The IHC results in HPA database showed that SCN4B expressed higher in normal tissues than in tumor tissues in tissue level." (PMID 37826914, 2023). "We then studied the involvement of the SCN4B gene and its expression product, the SCN4B/β4 protein, in tumour progression." (PMID 27917859, 2016). "SCN4B/β4 is almost absent in high-grade tumours and metastases." (PMID 27917859, 2016). "SCN4B/β4 protein was weakly expressed or totally absent in most grade II and III primary tumours studied, as well as in LNM." (PMID 27917859, 2016).
cardiovascular diseases (1 paper, 2019). "In fact, we could observe that the only gene with a lack of disease association is the SCN4B which is associated with cardiovascular diseases only." (PMID 31718537, 2019). "For cardiovascular diseases, DAVID search found more diseases than the systematic review and the exhaustive review, with the exception of a connection between the gene SCN4B and “other heart diseases” category retrieved by the exhaustive review but not by DAVID or systematic searches." (PMID 31718537, 2019).
SCN4B also shares sentences with these, for which no sentence is quoted: neurodegenerative disease (3 papers); Dravet syndrome (2); cardiac arrhythmias (1); cardiomyopathies (1); channelopathies (1); Cognitive impairment (1); depression (1); developmental delay and (1); dilated cardiomyopathy (1); headache disorder (1); heart diseases (1); heart failure (1); hypertrophic cardiomyopathy (1); hypopharyngeal carcinoma (1); metastatic tumours (1); motor neuron disease (1); muscular dystrophy (1); neuropathic pain (1); overnutrition (1); periodontitis (1); sudden infant death syndrome (1); Temple-Baraitser syndrome (1); Timothy syndrome (1); ventricular tachycardia (1).